H2BC6 (H2B clustered histone 6)
Description:
Core component of nucleosome. Nucleosomes wrap and compact DNA into chromatin, limiting DNA accessibility to the cellular machineries which require DNA as a template. Histones thereby play a central role in transcription regulation, DNA repair, DNA replication and chromosomal stability. DNA accessibility is regulated via a complex set of post-translational modifications of histones, also called histone code, and nucleosome remodeling. Has broad antibacterial activity. May contribute to the formation of the functional antimicrobial barrier of the colonic epithelium, and to the bactericidal activity of amniotic fluid.
Synonyms: H2B/h; H2BC4; H2BFH; HIST1H2BE; H2B.h; H2BC10; H2BC7; H2BC8; dJ221C16.8
Gene: Protein-coding gene on chromosome 6 (26,172,059 to 26,184,655, forward strand). Ensembl gene ENSG00000274290.
Subcellular location: Nucleus; Chromosome
Subcellular location (Human Protein Atlas): Nucleoplasm; Cytosol
Pathways (Reactome):
Gene expression (Transcription): B-WICH complex positively regulates rRNA expression; DNA methylation; ERCC6 (CSB) and EHMT2 (G9a) positively regulate rRNA expression; MLL4 and MLL3 complexes regulate expression of PPARG target genes in adipogenesis and hepatic steatosis; NoRC negatively regulates rRNA expression; PRC2 methylates histones and DNA; RNA Polymerase I Promoter Escape; RNA Polymerase I Promoter Opening; RUNX1 regulates genes involved in megakaryocyte differentiation and platelet function; RUNX1 regulates transcription of genes involved in differentiation of HSCs; Regulation of endogenous retroelements by KRAB-ZFP proteins; Regulation of endogenous retroelements by Piwi-interacting RNAs (piRNAs); Regulation of endogenous retroelements by the Human Silencing Hub (HUSH) complex; SIRT1 negatively regulates rRNA expression; Transcriptional regulation by small RNAs
Chromatin organization: CHD1 and CHD2 subfamily; CHD6, CHD7, CHD8, CHD9 subfamily; ChAHP complex assembly; HATs acetylate histones; HDACs deacetylate histones; Interaction of NuRD complexes with transcription factors; NuRD complex assembly
DNA Repair: Cleavage of the damaged purine; Cleavage of the damaged pyrimidine; Nonhomologous End-Joining (NHEJ); Processing of DNA double-strand break ends; Recognition and association of DNA glycosylase with site containing an affected purine; Recognition and association of DNA glycosylase with site containing an affected pyrimidine; Recruitment and ATM-mediated phosphorylation of repair and signaling proteins at DNA double strand breaks
Cell Cycle: Condensation of Prophase Chromosomes; Deposition of new CENPA-containing nucleosomes at the centromere; G2/M DNA damage checkpoint; Inhibition of DNA recombination at telomere; Packaging Of Telomere Ends
Developmental Biology: Activation of anterior HOX genes in hindbrain development during early embryogenesis; Chromatin modifications during the maternal to zygotic transition (MZT); Replacement of protamines by nucleosomes in the male pronucleus; Transcriptional regulation of granulopoiesis
Disease: Defective pyroptosis; Dengue Virus-Host Interactions
and 18 more pathways
Gene Ontology:
Molecular function: identical protein binding; protein binding; DNA binding; structural constituent of chromatin; protein heterodimerization activity
Biological process: antibacterial humoral response; antimicrobial humoral immune response mediated by antimicrobial peptide; defense response to Gram-positive bacterium; innate immune response in mucosa; chromatin organization; nucleosome assembly
Cellular component: extracellular exosome; extracellular region; nucleus; nucleoplasm; nucleosome; chromosome
Genetic constraint (gnomAD): Loss-of-function variants: 8 observed, 6.39 expected, observed/expected ratio (o/e) 1.25, 90% interval 0.72 to 1.88. That is too few expected variants to judge how well the gene tolerates losing a copy. Missense variants: 212 observed, 180.14 expected, observed/expected ratio (o/e) 1.18, 90% interval 1.05 to 1.32. Synonymous variants: 136 observed, 79.15 expected, observed/expected ratio (o/e) 1.72, 90% interval 1.49 to 1.93.
Homologues: Orthologues: chimpanzee H2BC4 (100% identical), macaque H2BC8 (100% identical), mouse H2bc4 (100% identical), mouse H2bc6 (100% identical), rat Hist1h2bc (100% identical). Paralogues in human: H2BC10 (100% identical), H2BC4 (100% identical), H2BC7 (100% identical), H2BC8 (100% identical), H2BC12 (99% identical), H2BC15 (99% identical), H2BC21 (99% identical), H2BC5 (99% identical), H2BC9 (99% identical), H2BC11 (98% identical), H2BC13 (98% identical), H2BC17 (98% identical), and 9 more.
Diseases named in the same sentence as H2BC6 in open-access papers:
H2BC6 is named in the same sentence as 1 disease in open-access papers, as found by Europe PMC text mining. Sharing a sentence is not in itself a finding about the gene and the disease. The quoted sentences say what the papers report.
cancer (2 papers, 2023 to 2024). A tumor composed of atypical neoplastic, often pleomorphic cells that invade other tissues. "In one of these cases, the mutated H2B-encoding gene (H2BC6) was among those histone genes harboring the highest average VAFs at pan-cancer level, consistent with clonality." (PMID 37640703, 2023).